MAPK3 (mitogen-activated protein kinase 3)
Diseases named in the same sentence as MAPK3 in open-access papers (continued):
Sharing a sentence is not in itself a finding about the gene and the disease.
endothelial dysfunction (41 papers, 2013 to 2026). In vascular diseases, endothelial dysfunction is a systemic pathological state of the endothelium (the inner lining of blood vessels) and can be broadly defined as an imbalance between vasodilating and vasoconstricting substances produced by (or acting on) the endothelium. "Conversely, MAPK3 detection restricted to vascular endothelial cells implicates its involvement in monocyte recruitment and endothelial dysfunction." (PMID 41503916, 2026).
myocardial infarction (40 papers, 2013 to 2026). Gross necrosis of the myocardium, as a result of interruption of the blood supply to the area, as in coronary thrombosis. "In an acute myocardial infarction rat model, miRNA-15b was demonstrated to deteriorate cardiomyocyte apoptosis by post-transcriptionally down-regulating the expression of BCL-2 and MAPK3." (PMID 33706714, 2021).
myocardial ischemia (39 papers, 2012 to 2026). A disorder of cardiac function caused by insufficient blood flow to the muscle tissue of the heart. "Based on the results of network pharmacology analysis, first, the top four genes (PRKCA/MAPK3/PRKCG/PLA2G4A) and PRKCE (an isoform of the large PKC family) were picked up for validation in the animal model of surgery-induced myocardial ischemia." (PMID 35141226, 2022).
Cognitive impairment (38 papers, 2011 to 2025). Abnormal cognition is characterized by deficits in thinking, reasoning, or remembering. "All naturally occurring mutations in the genes encoding ERK1/2 (MAPK1 and MAPK3) in humans, including mutation in noncoding regions of the genes, lead to cognitive impairment." (PMID 37817178, 2023).
Alzheimer disease (33 papers, 2011 to 2025). A progressive, neurodegenerative disease characterized by loss of function and death of nerve cells in several areas of the brain leading to loss of cognitive function such as memory and language. "Accumulated evidence have shown that up-regulation of MAPK3 (ERK1) are associated with the progression of Alzheimer's disease." (PMID 25379732, 2014). "For example, MAPK3 is a shared gene by Alzheimer's Disease (AD), Prion, Major Depressive Disorders (MDD), and Frontotemporal lobar degeneration (FTLD), indicating that these diseases might have some shared mechanism." (PMID 30618562, 2018). "In the Alzheimer’s disease pathway which contained 30 MFS-AD-treating targets, more targets were related to protease and serine/threonine–protein kinase, including two core targets, AKT1 and MAPK3." (PMID 36712676, 2022).
psoriasis (33 papers, 2012 to 2025). An autoimmune condition characterized by red, well-delineated plaques with silvery scales that are usually on the extensor surfaces and scalp. "Among the key target genes, MAPK3 and RELA were connected to all four psoriasis-related pathways, highlighting their critical role in the therapeutic mechanism of SHTLS." (PMID 40507893, 2025). "Additionally, proteins such as MAPK3, MAPK14, JAK2, and STAT1 were identified as having a direct impact on psoriasis-related disease proteins." (PMID 39590306, 2024).
ischemic stroke (31 papers, 2013 to 2026). A stroke disorder caused by obstruction of blood flow to the brain, due to thrombotic (local blood clot formation) or embolic (due to a blood clot or other material traveling from another site) event. "Notably, MAPK3, MAPK1, HSP90AA1, STAT3, PIK3R1, PIK3CA, and AKT1 were the main target proteins involved in the pathogenesis of ischemic stroke with Qi deficiency and blood stasis syndrome." (PMID 35401166, 2022). "On the basis of the KEGG enrichment analysis of network pharmacology, the MAPK signaling pathway was one of the main signaling pathways of RPR in treating ischemic stroke, and the PPI network displayed the main target as MAPK3 (ERK 1) and MAPK14 (p38)." (PMID 39771032, 2024). "Furthermore, through network pharmacology and molecular docking, four core targets (MAPK3, TNF-α, MAPK14, and JNK) closely related to RPR’s treatment of ischemic stroke were identified, exhibiting strong affinity with two key active components of RPR: albiflorin (AF) and β-sitosterol (BSS)." (PMID 39771032, 2024).
oral squamous cell carcinoma (28 papers, 2013 to 2025). "Secreted exosomal CMTM6 of oral squamous cell carcinoma induces M2-like macrophage polarization and promotes malignant progression via the MAPK3/MAPK1 signaling pathway." (PMID 36091768, 2022).
autism (26 papers, 2013 to 2025). Persistent deficits in social interaction and communication and interaction as well as a markedly restricted repertoire of activity and interest as well as repetitive patterns of behavior. "MAPK3 was associated with autism in several genome-wide association studies, copy number variants studies, and also one of the biomarkers proposed to detect the early stage of Alzheimer." (PMID 36691005, 2023). "Altered Ras/MAPK signaling has been identified as a common downstream mediator of divergent genetic mutations linked to autism, and MAPK3/ERK1 is present in a region of 16p11.2 mutated in ~1% of cases of autism." (PMID 26848828, 2016). "In addition, studies have found that deletion of chromosome 16 is associated with autism, and the MAPK3 gene encoding ERKl protein is located on chromosome 16." (PMID 32273901, 2020). "Pathway analysis of differentially expressed genes in the ASD group identified molecular networks linked to nervous system disorders, synaptic plasticity, and the canonical autism signaling pathway, involving key nodes such as Mapk3 and Homer1." (PMID 40801633, 2025). "Mutations in components of the MAPK signaling pathway, termed the RASopathies, produce numerous neurodevelopmental disorders, including autism, and the MAPK3 gene has been suggested to contribute to the head size changes in 16p11.2 individuals." (PMID 35623351, 2022). "This interval described by us and in the literature, contains several genes suspected to have a role in autism, especially the MAPK3 gene, which expresses the MAP kinase protein (ERK1)." (PMID 26742492, 2016). "MAPK3 is related to autism, neurodegenerative diseases and bipolar disorder, and can exacerbate nervous system diseases." (PMID 26742492, 2016). "Interestingly, a 593-kb deletion in chromosome 16p11.2, one of the most common CNVs associated with autism, contains the MAPK3 (ERK1) gene." (PMID 25874073, 2014). "Double Mvp+/−;Mapk3+/− male mice showed normal body weight as well as normal motricity, coordination, reward-seeking behaviors, working and short-term memory, associative learning, circadian activity, and no signs of autism and schizophrenic-like behaviors." (PMID 37968726, 2023).
rheumatoid arthritis (26 papers, 2009 to 2025). A chronic, systemic autoimmune disorder characterized by inflammation in the synovial membranes and articular surfaces. "We discovered that higher plasma MAPK3 levels could reduce the risk of rheumatoid arthritis (RA), while higher plasma ITIH1 levels might increase the risk of bipolar and reduce the risk of chronic ischemic heart disease." (PMID 38540773, 2024). "In rheumatoid arthritis, upregulation of LINC02381 can complement with miR-590-5p to reduce its level in RA tissues and inhibit the expression of mitogen-activated protein kinase 3 (MAP2K3) at the post-transcription level." (PMID 35391800, 2022).
head and neck squamous cell carcinoma (25 papers, 1999 to 2025). A squamous cell carcinoma that arises from any of the following anatomic sites: lip and oral cavity, nasal cavity, paranasal sinuses, pharynx, larynx, and salivary glands. "The results showed that the mRNA and protein expression of GSK3B, PIK3CA, FN1, MET, and SPP1 was significantly upregulated in head and neck squamous cell carcinoma tissues, while MAPK3 was significantly downregulated." (PMID 39323640, 2024).
osteoporosis (24 papers, 2011 to 2025). A condition of reduced bone mass, with decreased cortical thickness and a decrease in the number and size of the trabeculae of cancellous bone (but normal chemical composition), resulting in increased fracture incidence. "MAPK3 (also known as ERK1) is a member of the MAPK-signaling pathway; studies have found that activated MAPK can reduce the differentiation of osteoclasts, promote the generation of osteoblasts, and improve osteoporosis." (PMID 34671409, 2021).
acute myeloid leukemia (23 papers, 2009 to 2025). Acute myeloid leukemia (AML) is a group of neoplasms arising from precursor cells committed to the myeloid cell-line differentiation. "HQ exposure downregulated the mRNA levels of MAP 2 K2 and MAPK3 in chronic myeloid leukemia and acute myeloid leukemia pathway." (PMID 35366954, 2022). "The results of GSEA enrichment analysis showed that MAPK3 was significantly positively correlated with several pathways, including “ferroptosis” and “acute myeloid leukemia”." (PMID 36612069, 2022). "Encouragingly, MAPK3 and CD44, as hub genes, were not only enriched in “ferroptosis” and “acute myeloid leukemia” pathways but also significantly correlated with prognosis and immune cell infiltration in AML patients." (PMID 36612069, 2022).
renal carcinoma (23 papers, 2009 to 2025). A carcinoma arising from the epithelium of the renal parenchyma or the renal pelvis. "Moreover, MAPK3 activation/phosphorylation induces production of pro-angiogenic factors in renal carcinoma cells." (PMID 19788758, 2009).
epilepsy (22 papers, 2013 to 2025). A brain disorder characterized by episodes of abnormally increased neuronal discharge resulting in transient episodes of sensory or motor neurological dysfunction, or psychic dysfunction. "In the present study, we demonstrated that PTGS2, ESR1, MAPK1, PTPN11, and MAPK3 may be the targets of linoleic acid against epilepsy." (PMID 36034878, 2022).
Parkinson disease (22 papers, 2015 to 2025). A progressive degenerative disorder of the central nervous system characterized by loss of dopamine producing neurons in the substantia nigra and the presence of Lewy bodies in the substantia nigra and locus coeruleus. "Another example is the mitogen-activated protein kinase Erk1 (Mapk3), which was specifically enriched at dopaminergic synapses and has been linked to Parkinson’s disease via multiple cellular processes." (PMID 37918396, 2023).
schizophrenia (22 papers, 2008 to 2025). A major psychotic disorder characterized by abnormalities in the perception or expression of reality. "DOC2A and MAPK3, encoding double C2 domain alpha and mitogen-activated protein kinase 3, respectively, map to 16p11.2, duplication of which is associated with schizophrenia." (PMID 31691811, 2020). "In addition, expression of MAPK3 is significantly associated with a locus (rs4583255[T]) on 16p11.2 which shows genome-wide significant association with psychosis, including schizophrenia, bipolar disorder and related psychoses by a recent GWAS (genome-wide association study) in a large cohort." (PMID 25379732, 2014). "The identified PSD proteome (including a gene critical to synaptic plasticity—MAPK3) was significantly associated in gene set enrichment analysis with schizophrenia, validating independent reports of PSD enrichment in schizophrenia." (PMID 27898073, 2016). "Finally, the miR-137 validated target PKA signaling gene set (MAPK1, MAPK3, TCF4, and PTGS2) is of particular interest given that enrichment of schizophrenia-risk associated variants within these targets was replicated in an independent cohort." (PMID 25941532, 2015). "In addition to previously discussed findings implicating MAPK3 in schizophrenia, we note that MAPK3 RNA expression is also found to be increased in the postmortem frontal cortex from people with schizophrenia, in contrast with controls, in the study of Gandal and colleagues." (PMID 31691811, 2020). "The core identified targets of aripiprazole include MAPK3 (mitogen-activated protein kinase 3), PPARG (peroxisome proliferator-activated receptor gamma), the D2 receptor, and ESR1 (estrogen receptor 1), providing new insights into the mechanisms of this drug in schizophrenia treatment." (PMID 40572510, 2025). "MAPK3 could regulate the neurodevelopment in ASD and schizophrenia." (PMID 39039444, 2024).
cardiomyopathy (21 papers, 2012 to 2025). A disease of the heart muscle or myocardium proper. "Moreover, we showed that MAPK3 has the highest distribution property in this network which could affect the cardiomyopathy mechanism." (PMID 35311161, 2022). "The components of the MAPK pathway, such as MAP2K1 through MAPK3, as well as the Ras-related proteins, RAP1A, RAP1B, and M-Ras, had a median 2.6-fold (IQR, 2.0-fold to 15.5-fold) upregulation among patients with SARS-CoV-2 infection compared with patients with noninflammatory cardiomyopathy." (PMID 34910083, 2022).
type 2 diabetes (21 papers, 2012 to 2025). "MAPK3, and AKT1 were involved in Insulin signaling pathway (hsa04910), and Type II diabetes mellitus (hsa04930)." (PMID 34017037, 2021).
Anxiety (20 papers, 2012 to 2026). Intense feelings of nervousness, tension, or panic often arise in response to interpersonal stresses. "MAPK3 expression might also be altered in the brain of patients as MAPK phosphorylation levels in the amygdala were directly associated with anxiety symptoms in a previous study." (PMID 37181876, 2023). "We also recapitulate a previously reported genetic interaction and show that Mvp+/−;Mapk3+/− mice exhibit behavioral deficits, notably decreased anxiety-like traits detected in the elevated plus maze and open field paradigms." (PMID 37968726, 2023). "The overexpression of MAPK3 may indicate the pathogenesis of fear, anxiety and related psychopathological conditions." (PMID 27917343, 2016).
adenoma (17 papers, 2005 to 2024). A neoplasm arising from the epithelium. "Adenomas also showed marked accumulation of β-catenin and high expression of the β-catenin target, c-MYC, and frequent phosphorylation of ERK1/2 (MAPK3/1), a marker of MAPK pathway activation, and a known driver of intestinal tumorigenesis." (PMID 29419487, 2018).
diabetic retinopathy (16 papers, 2013 to 2025). "A previous research indicated that MAPK3 is a key target for treatment of rats with diabetic retinopathy." (PMID 35024051, 2022). "In addition, studies have shown that MAPK3 is involved in diabetic retinopathy development through autophagy regulation." (PMID 40351428, 2025).
memory impairment (13 papers, 2016 to 2025). "As predicted by network pharmacology methods, CASP3, BDNF, MAPK3, CREB1, and DRD2 were the hub genes in krill oil to alleviate METH-induced memory impairment." (PMID 34776973, 2021).
RASopathies (12 papers, 2018 to 2025). "Abnormal extracellular signal-regulated kinase 1/2 (ERK1/2, encoded by Mapk3 and Mapk1, respectively) signaling is linked to multiple neurodevelopmental diseases, especially the RASopathies, which typically exhibit ERK1/2 hyperactivation in neurons and non-neuronal cells." (PMID 38826084, 2024).
meningioma (10 papers, 2012 to 2025). A generally slow growing tumor attached to the dura mater. "Also, the gene expression profiling of MAPK3 showed downregulation, while the protein was upregulated in meningiomas." (PMID 28938569, 2017).
metabolic syndrome (10 papers, 2016 to 2025). A cluster of metabolic risk factors for CARDIOVASCULAR DISEASES and TYPE 2 DIABETES MELLITUS. "Using in silico data analysis, we created an mRNA-miRNA panel (ZBP1, HSPA1B, MAPK3 & mir-5192) associated with pancreatic cell dysfunction and metabolic syndrome and involved in necroptosis-related TNF pathway." (PMID 38961451, 2024). "Taking pigs with metabolic syndrome (MetS), for example, advanced senescence in MSCs from MetS animals was confirmed and miR-27b seemed to provoke the process by stimulating MAPK3 and p16, though the exact mechanism of how the background information was sensed remains to be explored." (PMID 33816501, 2021).
acute kidney injury (8 papers, 2021 to 2025). Sudden and sustained deterioration of the kidney function characterized by decreased glomerular filtration rate, increased serum creatinine or oliguria. "FGFR2 was found to be important in protection against the apoptosis of tubular cells in acute kidney injury, partly by stimulating the activation of extracellular signal-regulated kinase 1/2 (Erk1/2; also called mitogen-activated protein kinase 3/1)." (PMID 34360633, 2021).
HCMV infection (8 papers, 2005 to 2023). "The most important protein targets based on its degree from the C-T-P-D network were TNF, MAPK1, MAPK3, IL6, IL1B, AKT1 and CASP3 and the most important pathways associated with these protein targets were “Pathways in cancer”, “IL-17 signaling pathway”, and “Human cytomegalovirus infection”." (PMID 36591238, 2022).
cyst (7 papers, 2012 to 2022). A sac-like closed membranous structure that may be empty or contain fluid or amorphous material. "Two conserved Glycine max (soybean) mitogen activated protein kinase 3 (MAPK3) paralogs function in defense to the parasitic soybean cyst nematode Heterodera glycines." (PMID 35763120, 2022).
hyperuricemia (7 papers, 2017 to 2024). An abnormally high level of uric acid. "The core targets of Plantaginis Herba for the treatment of hyperuricemia were AKT1, mitogen-activated protein kinase 3 (MAPK3), MAPK1, tumor necrosis factor (TNF), prostaglandin-endoperoxide synthase 2 (PTGS2), sirtuin 1 (SIRT1), estrogen receptor 1 (ESR1), and androgen receptor (AR)." (PMID 33897800, 2021).
inflammatory bowel disease (7 papers, 2018 to 2023). A spectrum of small and large bowel inflammatory diseases of unknown etiology. "MAPK3 is downregulated in the dorsal root ganglion of sensory neurons in neuropathic pain, but has also been shown to be upregulated in colon tissues with Inflammatory Bowel Disease (IBD)." (PMID 35295473, 2021).
autism spectrum disorder (6 papers, 2016 to 2024). A spectrum of developmental disorders that includes autism, and Asperger syndrome. "Mapk3 is involved in pathways of cholinergic synapse and glutamatergic synapse, and closely related to the assembly, shape, function, plasticity and autism spectrum disorders of synapses." (PMID 33332355, 2020).
Hepatitis (6 papers, 2013 to 2025). Inflammation of the liver. "GSEA analysis indicated that MAPK3 is significantly enriched in antiviral pathways, including those related to influenza, hepatitis B, and measles viruses, suggesting its pivotal role in the host antiviral defense." (PMID 40872527, 2025).
influenza (6 papers, 2012 to 2025). An acute viral infection of the respiratory tract, occurring in isolated cases, in epidemics, or in pandemics; it is caused by serologically different strains of viruses (influenzaviruses) designated A, B, and C, has a 3-day incubation period, and usually lasts for 3 to 10 days. "Additionally, KEGG and GO enrichment analyses further supported these findings by demonstrating significant enrichment of MAPK3 in signaling pathways related to influenza, hepatitis B, and measles viruses." (PMID 40872527, 2025).
kidney cancer (6 papers, 2016 to 2024). Primary or metastatic malignant neoplasm involving the kidney. "Perhaps this difference in the expression of the genes encoding the two ERK1/2 isoforms indicates that the MAPK3 gene is more active in this type of kidney cancer." (PMID 37373509, 2023).